CCT2 (chaperonin containing TCP1 subunit 2)
Diseases named in the same sentence as CCT2 in open-access papers (continued):
Sharing a sentence is not in itself a finding about the gene and the disease.
Sensory neuropathy (1 paper, 2019). Peripheral neuropathy affecting the sensory nerves. "A mutation in cct2 has been found in a family with Leber congenital ameurosis retinal phenotype and mutations in cct4 and cct5 have been related to sensory neuropathy." (PMID 30777146, 2019).
soft tissue sarcoma (1 paper, 2019). A malignant neoplasm arising from muscle tissue, adipose tissue, blood vessels, fibrous tissue, or other supportive tissues excluding the bones. "Clinical data from the GEPIA dataset confirms that CDK4, CCT2, and MGAT1 expression levels are highly correlated with prognosis, and that up-regulation may lead to a significant reduction in survival time in patients with soft tissue sarcoma." (PMID 32117430, 2019).
tauopathies (1 paper, 2025). "In tauopathies, TRiC subunits such as CCT2, CCT3, CCT5, and CCT7 have been shown to inhibit tau aggregation and we show here the dramatic CCT2-mediated protection against tau toxicity in transgenic flies." (PMID 40693240, 2025).
cancer (32 papers, 2013 to 2025). A tumor composed of atypical neoplastic, often pleomorphic cells that invade other tissues. "The data from T47D cells show that overexpressing CCT2 can result in the uncontrolled proliferation and the metastatic-like behavior of aggressive, invasive cancer cells and is linked to increased expression of cell cycle regulators." (PMID 33996588, 2021). "In most cancers, CCT2 expression was high and was associated with poor prognosis." (PMID 36119498, 2022). "This expression difference also responds to the possibility that CCT2 may be closely associated with the development of colonic inflammation or cancer." (PMID 35372018, 2022). "Moreover, CCT2 gene expression was negatively correlated with infiltration of most immune cells in 10 cancer types, and CCT2 expression was related to tumor mutation burden and microsatellite instability." (PMID 36119498, 2022). "Future research focus on investigating the underlying molecular mechanisms of CCT2 in promoting cancer might yield novel insights for possible treatments by targeting CCT2." (PMID 33869000, 2021). "CCT2 was needed for tumor growth, indicating that this single subunit could be a viable therapeutic and diagnostic target in cancer." (PMID 31964905, 2020). "Hence CCT2 is part of an amplicon that is associated with cancer development." (PMID 33996588, 2021). "As a step towards answers, our study identifies CCT2 as a potential target for therapeutic inhibition as well as diagnostic development, whose loss could impede the activity of the chaperonin complex in a manner that is detrimental to cancer cells." (PMID 31964905, 2020). "Several CCT subunits, such as CCT2, CCT3, CCT4, CCT5, CCT6A, and CCT7, have been implicated in cancer progression." (PMID 40867231, 2025). "These proteins—such as HSP90ab1, eEF1α1, c-Myc and CCT2—play critical roles in cancer cell growth and survival by regulating protein stability, synthesis and transcription." (PMID 40855114, 2025). "According to functional analysis, CCT2-loaded exosomes facilitated cancer growth, as well as the dissemination of metastasis through the activation of the JAK2/STAT3 signaling pathway." (PMID 41294803, 2025). "The data revealed that ARV facilitates the binding of ARV σC protein to CCT2, resulting in a decreased interaction between CCT2 and IκBα in A549 cancer cells." (PMID 41334925, 2025). "This, in turn, enhances the CCT2‐mediated folding of the Gli‐1 protein, thereby promoting cancer metastasis." (PMID 38363102, 2024). "CCT2 functions as an oncogenic gene to participate in the progression of various cancers, such as gastric cancer, colorectal cancer and HCC." (PMID 38166853, 2024). "I-Trp disrupted protein-protein interactions between the CCT and tubulin, specifically targeting cancers that overexpress CCT2." (PMID 35602608, 2022). "CCT2-depleted cancer cells were resistant to killing with CT20p, while cancer cells highly expressing CCT2 were sensitive." (PMID 35602608, 2022). "In particular, expression of the second CCT subunit, CCT2, correlated with increased tumor stage and aggression while inversely correlating with cancer patient outcomes." (PMID 36185250, 2022). "Despite increasing evidence supporting the important role of CCT2 in the tumorigenesis of certain cancers, few articles that provide a systematic pan-cancer analysis of CCT2 have been published." (PMID 36119498, 2022). "In many cancers, the genes encoding CCT subunits are genomically amplified and found in chromosomal hotspots (e.g., CCT2)." (PMID 35602608, 2022). "In our published study of the role of CCT2 in the proliferation of cancer cells, we generated T47D cells that expressed exogenous CCT2 tagged with FLAG (T47D-CCT2)." (PMID 35749519, 2022). "These CD44 positive cells were absent in the blood-alone control lacking MDA-MB-231 cells, confirming the results from the CSS Analyzer II where the CCT2 stain was used to detect spiked cancer cells." (PMID 35749519, 2022).
cancer (continued). "The role that CCT2 plays in tumorigenesis and tumor immunity suggests that it can serve as a prognostic marker in many cancers." (PMID 36119498, 2022). "In this study, we report that CCT2 expression is increased in primary cancer and metastatic tissue compared to normal tissue, and this inversely correlated with patient OS." (PMID 35749519, 2022). "In distinction, most reports to this point are restricted to investigations on the role of CCT2 in specific styles of cancer." (PMID 36119498, 2022). "All eight CCT subunits showed significant (p< 0.0001) upregulation in RNAseq expression in cancer compared to normal tissue, with the strongest upregulation seen in CCT2 and CCT3, S1A Fig." (PMID 35749519, 2022). "To explore the correlation between CCT2 expression and the clinicopathological features of cancer, we evaluated CCT2 expression in patients with different grades and stages of cancer." (PMID 36119498, 2022). "Using CCT2 as a marker to identify circulating tumor cells in blood enhanced the ability to detect these cells from a broader range of cancers like small cell lung cancer (SCLC) that currently lack non-invasive diagnostics for patient management." (PMID 35602608, 2022). "In our study, we systematically analyzed the prognosis of CCT2 expression in various cancers and elaborated the correlation between CCT2 expression and tumor immunity." (PMID 36119498, 2022). "In this study, we examined CCT2 expression in cancer compared to normal tissues and found statistically significant increases in tumors." (PMID 35749519, 2022). "Previously, we found that expression of the second subunit (CCT2 or CCTβ) inversely correlated with cancer patient survival and was essential for tumorigenesis in mice, driving tumor-promoting processes like proliferation and anchorage-independent growth." (PMID 35749519, 2022). "To explore the connection between CCT2 expression and multiple infiltrating lymphocytes, we have a tendency to analyze the relative fraction of infiltrating immune cell sorts in 33 cancer sorts exploitation CIBERSORT." (PMID 36119498, 2022). "Such work aligns with our own study of CCT2 to improve the identification of cancer cells in blood and detect the most clinically relevant CTCs for monitoring patient outcomes." (PMID 35749519, 2022). "To directly evaluate CCT2 levels in tumor tissues, we used a pediatric cancer tissue microarray (TMA) for examining CCT2 protein by standard IHC." (PMID 36185250, 2022). "The importance of CCT2 in cancer progression is further emphasized by the fact that cancer patients with genetic alterations in CCT2 had reduced overall and progression free survival." (PMID 33996588, 2021). "BZW2 and CCT2 have been shown to promote the proliferation of various tumors and affect the prognosis of cancer." (PMID 34696677, 2021). "Most of our understanding of the role of CCT2 in cancer is inferred from the activity of the whole CCT folding complex and identified protein-protein interactions." (PMID 33996588, 2021). "To determine the mRNA levels of CCT2 in multiple human cancers, we analyzed expression of CCT2 using RNA-sequencing (RNA-seq) data derived from TCGA database." (PMID 33869000, 2021). "To validate the expression pattern of CCT2 in various cancers, we further analyzed CCT2 expression in 72-paired tissues across more than 68,000 samples using GENT2 database." (PMID 33869000, 2021). "Significant upregulation of TCP1, CCT2/3/5/6A/8 levels have been found in a variety of cancers, with CCT3/6A/8 the best studied in HCC, while there are few studies on CCT4/5/7." (PMID 34676169, 2021). "Low levels of HSP90AB1/TRAP1, HSPA6/TRAP1, and HSP90AA1/TRAP1 in urine increase the probability of the patient having cancer, whereas low levels of CCT2/HSP90AB1 and HSPB1*HSPA9 in urine are strongly associated with non-cancer groups." (PMID 34692733, 2021).
cancer (continued). "To this end, we mined pan-cancer databases like TCGA for the expression of CCT subunits in all cancers and showed that the most common type of copy number alteration of the CCT2 subunit gene was amplification, and that this gene was rarely deleted." (PMID 33996588, 2021). "Some of the genes were reported as cancer-related genes, such as CCT2, CCT3, CCT4, CCT6A, CCT7, CCT8." (PMID 33897772, 2021). "In total, these findings provide additional support for CCT2 in promoting the proliferation of cancer cells and growth of spheroids." (PMID 33996588, 2021). "Exogenous CCT2 increased the proliferation of cancer cells, resulting in larger and multiple spheroids as compared to control cells." (PMID 33996588, 2021). "Conversely, the high expression of other four HSPs (HSP90AA1, CCT1, CCT2, CCT6A) was associated with poor prognosis (survival Z-score > 0) for most types of cancer." (PMID 31101846, 2019). "Although their clinical importance was well studied in other cancers, the expression of CCT2 and PDIA3 and their clinicopathological significance in gallbladder cancer have never been investigated." (PMID 23782473, 2013). "Likewise, CCT2 has been proposed as a marker for circulating tumor cells, emphasizing the CCT complex’s diagnostic and therapeutic relevance in cancer." (PMID 41516249, 2025). "As a result, hsa_circ_001726 may have a more prominent role as a therapeutic target in cancer treatment compared to its parental gene CCT2." (PMID 38166853, 2024). "The addition of CCT2 staining to the CSS led to improved recovery of cancer cells spiked into blood, including those with mesenchymal features, providing visual differences that could help classify CTCs." (PMID 35749519, 2022). "The aim is to investigate the function of CCT2 in various cancers." (PMID 36119498, 2022). "Our studies demonstrate that detection of CCT2 could identify rare cancer cells in blood and has application in liquid biopsy approaches to enhance the use of minimally invasive methods for cancer diagnosis." (PMID 35749519, 2022). "In addition, our enrichment analysis suggests that CCT2 can potentially influence cancer etiology or pathogenesis through HEDGEHOG SIGNALING." (PMID 36119498, 2022). "In this study, we examined the expression of the second CCT subunit, CCT2, using genomic databases of adult and pediatric tumors and normal tissues, and found that it was highly expressed in pediatric cancers, showing a significant difference compared to normal tissues." (PMID 36185250, 2022). "We also evaluated the prognostic worth of CCT2 in pan-cancer as supported by the TCGA dataset." (PMID 36119498, 2022). "MDM2 is also in the same chromosomal amplicon as CCT2 that is highly expressed in cancer cells." (PMID 35602608, 2022). "The detection of CK-/CCT2+ cancer cells with the CSS platform suggested that the use of CCT2 as a marker could help establish prognostic thresholds for cancers that currently lack validated liquid biopsy methods." (PMID 35749519, 2022). "Research from our lab and others showed that CCT2 is upregulated in multiple adult cancers." (PMID 36185250, 2022). "To identify which pediatric cancers might benefit from developing CCT2 as a molecular target, we analyzed the KidsFirst/CBTTC cohort and the TARGET Pan-Cancer cohort by cancer type." (PMID 36185250, 2022). "CCT2 played a pivotal role in clinical tubulin-binding agent-resistant or CCT2-overexpressing cancers, and targeting the β-tubulin/CCT2 complex might provide these cancers with a novel chemotherapeutic strategy." (PMID 33815471, 2021). "A complete knockdown of CCT2 is not possible because CCT2 is an essential gene (depmap.org), and its loss causes death of cancer cells." (PMID 33996588, 2021).
cancer (continued). "MYC, CDK2, and cyclin D1 (highlighted by red circles) as part of the CCT2 interactome are shown, supporting that CCT2 could be a central point or node for regulation of cancer proliferation pathways mediated by these factors." (PMID 33996588, 2021). "But whether CCT2 is an essential component of the chaperonin’s activity in cancer cells and promotes tumorigenesis is unknown." (PMID 31964905, 2020). "Our research with CCT2 suggests that the individual CCT subunits may have different roles in the activity of the chaperonin complex in cancer cells that remain to be studied." (PMID 31964905, 2020). "We found that these cancers expressed higher levels of CCT2 as compared to normal tissues." (PMID 29299146, 2017). "Moreover, CCT2 is overexpressed in certain malignant tumors and its overexpression is closely correlated with poor prognosis." (PMID 24809979, 2014). "Pan-cancer research on the association between CCT2 and varied cancers has not been reported." (PMID 36119498, 2022). "Hence, to evaluate the expression status and prognostic significance of CCT2 in pan-cancers, an analysis of the relationship between CCT2 and different tumor immune cell infiltrations was conducted using datasets from the Cancer Genome Atlas, Cancer Cell Lineage Encyclopedia, and so on." (PMID 36119498, 2022). "Therefore, assessing CCT2 protein levels in cancer cells/tissues could provide clinicians with information on tumor progression and metastatic potential." (PMID 35749519, 2022). "To address this, we show that overexpressing one subunit, CCT2, is sufficient to promote the proliferation of cancer cells and enhance the potential for metastasis, suggesting that this subunit could be targeted to inhibit the carcinogenic activity of the complex." (PMID 33996588, 2021). "Cancer cells over‐express different subunits of the chaperonin, such as CCT1 and CCT2, which promotes survival and migration." (PMID 37328936, 2023). "Importantly, among these markers, MYCN and CCT2 expression showed the highest t-values, indicating a distinct difference between the two sample types, which suggests that the difference in CCT2 gene expression between cancer and normal tissues is more likely to be true and reliable." (PMID 36185250, 2022). "Their analysis revealed the expression of CCT2 and the other CCT subunits in the EVs of several cancers." (PMID 35749519, 2022). "To investigate how CCT2 staining impacted CTC visualization using CSS Analyzer II, we used the method of spiking a known number of cancer cells into a vial of freshly collected blood from healthy individuals." (PMID 35749519, 2022). "Hence CCT2 could be a viable target for therapeutic development in breast and other cancers." (PMID 31964905, 2020). "Based on the Oncomine database, we found that mRNA expressions of TCP1, CCT2, CCT6A, CCT7, STIP1 and HSP90AB1 were significantly upregulated in cancerous samples compared with normal samples in various types of cancer, including BC." (PMID 32194784, 2020). "The results showed that the expression of CDK4, CCT2, and MGAT1 in LMS tissues was significantly higher than that in adjacent tissues and an important member of the cancer signaling pathway." (PMID 32117430, 2019). "Consequently, the decreases in CCT2 resulted in activation of CD4+ T cells and inhibition of cancer growth." (PMID 41294803, 2025). "An operator then sorted the sample through the CSS Analyzer II events to select spiked cancer cells based on 1) CTC criteria from the CXC kit and 2) positive signal in the PE channel (column five) for anti-CCT2 antibody staining intensity as described in the methods." (PMID 35749519, 2022). "To confirm that the (CK-/CCT2+) cells detected in our analysis were the cancer cells that we originally spiked and not random blood cells from the donor, we stained for CD44, a tumor marker associated with MDA-MB-231 cells." (PMID 35749519, 2022).
cancer (continued). "Detection of CCT, and specifically CCT2, is independent of cancer type or lineage markers and is based upon a biological function that is upregulated in cancers, especially those with invasive features." (PMID 36185250, 2022). "We demonstrated that CCT2 staining could be incorporated into a CTC capture and staining protocol, providing biologically relevant information to improve detection of cancer cells shed in blood." (PMID 35749519, 2022). "We found that CCT2 expression drove the proliferation of cancer cells in spheroid cultures as well as in 2D monolayers, endowing cancer cells with growth adaptivity irrespective of anchorage." (PMID 33996588, 2021). "Using combined pan-cancer studies, moderately positive correlations of CCT2 mRNA were found with MYC, CDK2, CDK4, CCNE1 but not CCND1 (slight negative correlation)." (PMID 33996588, 2021). "CCT is thus a viable target for therapeutic intervention in cancer due to its function as a critical protein-folding complex, and the inhibition of CCT could be achieved through direct targeting of the CCT2 subunit." (PMID 31964905, 2020). "Finally, it is important to note that while some leukocytes are CCT2 positive (light blue arrow in row 3), this is not always the case (yellow arrows in rows 8 and 12), and leukocytes are ruled out as cancer cells due to positive CD45 signal." (PMID 35749519, 2022). "Having shown that CCT2 staining works in a standard CTC detection protocol using cancer cells spiked into blood, we performed a small pilot study using blood from SCLC patients to determine if CCT2 staining could detect CTCs released into blood in these patients." (PMID 35749519, 2022). "CCT2 is an intracellular protein that may not be subject to the variability of plasma membrane turnover or shedding and is highly expressed in multiple cancers, giving it a potentially broader application base." (PMID 35749519, 2022). "Because CCT2 may drive biological processes that are independent of cancer lineage markers and increases with advanced cancer stage, CCT2 could be a novel marker for detection of CTCs that helps enumerate as well as inform on tumor metastatic potential." (PMID 35749519, 2022).